IL1A (interleukin 1 alpha)
Diseases named in the same sentence as IL1A in open-access papers (continued):
Sharing a sentence is not in itself a finding about the gene and the disease.
infection (continued). "The lung lesions observed in the absence of both IL-1α and IL-1β were similar to those seen in mice deficient for IL-1R1 or TNF, although confluent necrosis was more pronounced in the absence of TNF 4 weeks post-infection." (PMID 25400917, 2013). "Absence of Vpr downregulated several proinflammatory molecules such as IL-1α, IL-1β, IL-8 compared to HIV-1wt-infected culture in infection phase, suggest that Vpr could have a specific effect in activating proinflammatory factors, either directly or through enhanced viral replication." (PMID 22727020, 2012). "Using chemiluminescent imaging we measured the concentrations of IL-1a, 1b, 2, 4, 5, 6, 8, 10, 12 (p70), 13, 15, 17 and 23, IFN-γ, TNF-α and TNF-β in duplicate plasma samples available in bio-bank from 9 PI-CFS subjects and 12 recovered controls at 24 months post-infection." (PMID 22973830, 2012). "Together, these data demonstrate that IL-1β expression but not IL-1α expression is associated with WNV infection in humans and indicates that WNV infection triggers the inflammasome signaling pathway to induce IL-1β during infection." (PMID 23209411, 2012). "While IL-17R KO animals predictably had significantly higher amounts of IL-17 in brain abscess homogenates, several other mediators were also elevated between 7 and 14 days after infection, including IL-1α, IL-1β, IL-6, CCL3 and CXCL1 (data not shown), as well as CXCL2 and CXCL9." (PMID 22704602, 2012). "Furthermore, cytokine analysis showed that the IFN-γR−/− mice had significantly reduced levels of pro-inflammatory (IL-1α, IL-1β, and IL-6), IL-12p40, IL-17, and chemokine (G-CSF and CXCL1) production compared to WT mice during infection with C. neoformans strain H99γ." (PMID 21359196, 2011). "In a study based on a mice model, due to the effect of pro-inflammatory cytokines such as IL-1α′ and TNF-α′ in early infection, there was mild inflammation with low and stable concentrations of PGE2, which contributed to an efficient iNOS expression permitting temporal control of the infection." (PMID 19468469, 2008). "While IL-1α is known to play a crucial role in initiating and amplifying inflammation by alveolar macrophages, its regulation and function during Mab remains unknown, possibly due to a lack of studies specifically examining AMs during Mab infection." (PMID 40415550, 2025). "Thus, we hypothesized that in the absence of infection, in vivo M1-Macs are a significant source of IL-1α in the term human uterus, which can induce local P4 withdrawal in myometrium." (PMID 41227337, 2025). "However, prolonged IL-1α treatment (3 weeks) worsened disease outcomes through Th2 expansion, suggesting that IL-1α treatment may be promising for early infections but not for established CL." (PMID 39460345, 2024). "PAF C-16 can activate monocytes/macrophages by binding to PAFR and stimulate the production of inflammatory mediators such as TNF-α, IL-1α and β, reactive oxygen intermediate (ROI) and reactive nitrogen intermediate (RNI) species, and thus may play a protective role during infection." (PMID 32587578, 2020). "IL-1α has only recently emerged as an alarmin that rapidly initiates the production of pro-inflammatory mediators in a MyD88-dependent manner, thus promoting recruitment of neutrophils and macrophages to the site of infection as well as their activation independent of TLR signaling pathways." (PMID 30846984, 2019). "In contrast, IOE infection that fails to induce memory-like NK cells or provide a protective recall response to Ehrlichia promoted the production of inflammasome-dependent, pro-inflammatory cytokines, including IL-1α, IL-1β, and IL-18 (data not shown), and the immunosuppressive IL-10." (PMID 27092553, 2016). "We thus propose that the presence of IL-1α or IL-1β is sufficient to trigger IL-1R pathway, an essential component in the development of innate response to acute M. tuberculosis infection, but may not be sufficient for full control of the infection." (PMID 25400917, 2013).
infection (continued). "We measured Type 1 (IFN-γ, TNF-α, IL-2), Type 17 (IL-17, IL-22), and proinflammatory cytokines (IL-1α, IL-1β) in QuantiFERON (QFT) supernatants from TBI individuals with (TBI+Hel+) and without (TBI+Hel−) infection." (PMID 41583474, 2025). "Albeit the differences were small, infection-induced transcripts for COX-1, mPGES-1, and TNF-α appeared to be somewhat higher in the absence of IL-1α/β." (PMID 35523455, 2022). "In contrast, levels of MCP-1/CCL2, NGAL, sTNFRSF1A, CXCL9, MMP-9, lactoferrin, and IL-1α did not significantly change in patients between critical disease in the ICU and upon infection recovery post-ICU." (PMID 33232303, 2021). "IFN-β was secreted at low levels that did not vary significantly during infection, whereas IFN-α and IL-1α/β were produced in limited amounts and with kinetics similar to those of IL-6 and IP-10." (PMID 34607464, 2021). "infection of SCC cells did not affect mRNA levels of IL10, IL1β, IL1α, HBEGF, and GMCSF, compared with NS cells." (PMID 31912662, 2020). "VEGF and IFN-γ also did not have altered expression upon infection, and many samples did not have detectable amounts of IFN-γ, TNF-α, IL-1α, or IL-1β (data not shown)." (PMID 31289185, 2019). "Infection of PLEC with PA01 at 104 and 105 cfu/mL for 12 and 24 h induced cell injury and some cell death (data not shown) and triggered the release of IL‐1α." (PMID 26714197, 2016). "We found a significant increased production of IL-1α and IL-1β, but not IL-18, and of the cleaved fragment of procaspase-1 in the lungs of Cftr–/– than C57BL/6 mice during either infection." (PMID 26972847, 2016). "Infection with L. major increased the secretion of TNF-α, IL-6, TIMP-1, IL-1RA, G-CSF and TREM, but not IL-1α or IL-1β." (PMID 24416445, 2014). "Several cytokines, such as the granulocyte macrophage colony-stimulating factor (GM-CSF), IL-1α, TNF-α, IL-10, IL-17A, IL-2, IL-4 and IL-5, showed a slight but non-significant increase in their serum concentrations upon infection (data not shown)." (PMID 23776551, 2013). "Cytokine analysis of blood plasma samples collected 4 hours after infection revealed an increase in concentrations of IL-1α, IL-6, the CXC chemokine KC, G-CSF, MCP-1, and the CC chemokine eotaxin in WT but not in Trpm5–/– mice compared with concentrations before infection." (PMID 35503420, 2022). "In addition, WT cells exhibited similar amounts of IL-1α, IL-1β, and TNF-α release with and without treatment, but lower levels of CXCL1 and IL-6 in infection supernatants." (PMID 33441602, 2021). "Finally, infection stimulated IL-8 production in non-CF and CF AEC (p < 0.05) and correlated with IL-1α (r = 0.63 & r = 0.74 respectively; p < 0.0001)." (PMID 32328066, 2020). "Albeit not statistically significant, the levels of G-CSF, IL-1α, MCP-1/CCL2, MIP-2/CXCL2 at day 1, G-CSF, KC, MCP-1, and MIP-2 at day 2, and IL-1α, IL-1β, IL-6, IL-10, MCP-1, MIP-2, and TNF at day 3 post-infection were 1.5–4.4-fold higher in SIRT3/5−/− than in SIRT3/5+/+ mice." (PMID 31632409, 2019). "The current study also identifies several factors, including IL-1α, MIP-1α, RANTES, IL-12(p40) and IL-12(p70) that are induced in aged mice but not young mice following infection (compared to PBS) and other factors, including IL-1β, IL-10, IL-13 and eotaxin that are specific to young mice." (PMID 27936166, 2016). "Strikingly, IL-6, IL-1β, IL-1α, IL-10, MIP-1α, and KC (data not shown) were secreted at significantly higher levels in response to infection with C. caviae compared to C. muridarum, whereas G-CSF (data not shown), GM-CSF (data not shown), and TNF-α levels were similar between the strains." (PMID 22292031, 2012). "In vitro, MPXV infection of human cells does not induce interferon-stimulated gene (ISG) expression and further suppresses Tumour Necrosis Factor alpha (TNF-α), Interleukin 1 alpha and beta (IL-1α and β), C-C Motif Chemokine Ligand 5 (CCL5) and Interleukin 6 (IL-6) activation in primary fibroblasts." (PMID 35887214, 2022).
infection (continued). "Unlike Mycopar, the early induction at 2 MPV of IFN-γ, IL-1α, TNF-α, IL-17 and CXCL9 in pgsN and pgsNQ groups may help in controlling early infection with M. paratuberculosis and provide more protection against associated pathological lesions as was clearly shown in liver." (PMID 32957508, 2020). "Thus, with the possible exception of IL1A, which displayed an age-dependent upregulation in CPP, none of the MAP-specific differentially expressed cytokine genes identified by qRT-PCR at 12 months post-infection displayed significant age-dependent changes in transcript abundance." (PMID 32547548, 2020). "Interestingly, both CCR2+ inflammatory monocytes and monocyte-derived dendritic cells show increased transcription of the Il1a gene at 48 h post-A.fumigatus challenge, but whether lung-resident CCR2+ monocytes could contribute to IL-1α production at early times after infection was not explored." (PMID 25629406, 2015).
cancer (304 papers, 2002 to 2026). A tumor composed of atypical neoplastic, often pleomorphic cells that invade other tissues. "Interleukin-1 alpha (IL-1α), a proinflammatory cytokine, has been implicated in the progression of various cancers, but its role in OSCC remains poorly understood." (PMID 40940885, 2025). "A comprehensive cross-sectional analysis of cancer databases (cBioPortal) revealed that higher IL-1α expression in cancer cells was associated with a lower 5-year survival rate." (PMID 40940885, 2025). "IL-1α and IL-1β are key downstream factors in intrinsic and extrinsic pathways linked to inflammation and malignant tumors." (PMID 41333471, 2025). "The secretion of IL-1α by cancer cells is associated with constitutive NF-κB activation, which drives the expression of downstream target genes involved in progression, metastasis, and angiogenesis." (PMID 40497976, 2025). "In human tumors, we identified an enrichment for IL-1α-expressing monocyte-derived macrophages linked to age, poorer survival, and recurrence, unraveling how aging promotes cancer and offering actionable therapeutic strategies." (PMID 39236155, 2024). "Extensive research has been conducted on the role of cancer-associated fibroblasts (CAFs) in solid tumors, particularly in relation to their production of soluble factors such as IL-1α, IL-1β, CXCL1, CXCL12, G-CSF, and IL-6." (PMID 37880682, 2023). "FGF19 mediates the polarization of hepatic stellate cells to inflammatory cancer‐associated fibroblasts (iCAFs) by activating the autocrine effect of IL‐1α via the FGFR4‐JAK2‐STAT3 pathway." (PMID 37345586, 2023). "Polymorphism rs3783553 is associated with the regulation of the IL-1A expression levels, for interrupting a linking site to miRNA-122 and miRNA-378, and is thus associated with several kinds of malignant neoplasms." (PMID 36833388, 2023). "Bermekimap, a human IL-1α neutralizing antibody, was tested in patients suffering from different types of cancer, including advanced colorectal cancer, and reduced cancer-associated cachexia." (PMID 36293159, 2022). "Elevated IL-1α was also found to be associated with cancer stem cell (CSC) accumulation and poor metastasis-free survival in BCa patients." (PMID 35626710, 2022). "IL-1α and IL-1β, cytokines of the interleukin 1 family, have also been linked to the development of cachexia and muscle mass depletion in the context of malignancy or infectious diseases." (PMID 35743911, 2022). "By contrast, HLA-I+EMTlo cancer cells were associated with enhanced IL1A, IL1B, and CXCL5 mRNA expression." (PMID 35503263, 2022). "This includes IL‐1α, a master regulator of inflammation, which is linked to an increased risk of muscle wasting in cancer cachexia." (PMID 33956410, 2021). "In terms of cancer research, different case-control studies have suggested the association of IL1A, IL2, and IL6 with CRC." (PMID 34931923, 2021). "It is known that IL-1α is a significant driver of the proinflammatory mechanisms, which are often linked to chronic inflammatory diseases or cancer." (PMID 31612270, 2020). "In turn, TSLP was secreted by cancer-associated fibroblasts (CAFs) activated by IL-1α and IL-1β, which are products of cancer cells and tumor cell-conditioned macrophages." (PMID 33022971, 2020). "Single nucleotide polymorphisms (SNPs) in interleukin 1 alpha (IL1A) were reported to be correlated to the susceptibility of diverse cancers." (PMID 30819119, 2019). "Associations between single nucleotide polymorphisms in the IL-1α gene and cancer risk have been identified with carriers of the rs17561 missense mutation showing reduced susceptibility to clear cell ovarian cancer." (PMID 31231372, 2019). "Future research is needed to elucidate the mechanism by which exercise and Nexrutine decrease IL-1α concentrations and the role of IL-1a on cachexia and bone loss seen with cancer." (PMID 31856170, 2019).
cancer (continued). "IL-1α is an essential cytokine that contributes to inflammatory responses and is implicated in various forms of pathogenesis and cancer." (PMID 28993621, 2017). "On the other hand, IL-1α alters immune status, stimulates cytokines production and the proliferation of cancer-associated fibroblasts and promotes cancer progression." (PMID 26919242, 2016). "IL-1α, an important regulator of immune and inflammation responses, has been implicated in cancer development and prognosis." (PMID 27121322, 2016). "Importantly, elevated levels of IL-1α in human cancers were associated with worse prognosis following immunotherapy." (PMID 38746389, 2024). "In a mouse model of rectal cancer (CRC), neoadjuvant radiation therapy (5 fractions of 2 Gy) triggered an elevation of tumour-derived interleukin 1α (IL-1α), leading to the polarization of cancer-associated fibroblasts (CAFs) towards a pro-inflammatory phenotype." (PMID 38833685, 2024). "Both IL-1α and IL-1β participate in the systemic inflammation associated with cancer." (PMID 36072935, 2022). "In summary, while blockade of IL‐1α seems to be effective in reducing inflammation-associated symptoms such as cachexia or other cancer-related symptoms (pain, fatigue, anorexia) in patients with advanced malignant disease, a benefit in overall survival has so far not been shown." (PMID 33530653, 2021). "Anorexia in cancer patients is associated with the predominance of signals suppressing appetite in the hypothalamus—proopiomelanocortin and anorexigenic action of pro-inflammatory cytokines: IL-1α, IL-1β, IL-6, TNF-α." (PMID 33158194, 2020). "Additionally, BRAFV600E was shown to induce expression of factors such as IL-10 and IL-1α, which can induce tolerogenic forms of dendritic cells and cancer-associated fibroblasts (CAFs), respectively." (PMID 31762942, 2019). "Moreover, co-culture of pancreatic ductal adenocarcinoma cells with cancer-associated fibroblasts (CAFs) resulted in marked upregulation of multiple inflammatory factors including IL-1α." (PMID 31231372, 2019). "IL-1α has been reported to be associated with poor prognosis in a wide range of cancers." (PMID 31320902, 2019). "As aberrant NF-κB activity has been implicated in almost all steps of cancer development, we analyzed the dynamic regulation and activation status of the canonical NF-κB pathway in control and IL-1α-stimulated individual cells using proximity ligation assays (PLAs)." (PMID 31426445, 2019). "Accordingly, it is biologically reasonable that functional IL1A polymorphisms may play causal roles in the development of cancer." (PMID 30819119, 2019). "In cases of advanced cancers, bone mineral density loss is often observed and may be mediated via IL-1α." (PMID 31856170, 2019). "Increasing evidence has showed that IL1A polymorphisms are associated with several cancers." (PMID 30819119, 2019). "Recently, many studies have tested the association between different forms of cancer and functional variants of genes responsible for the inflammatory process, such as interleukin 1A (IL1A), interleukin 4 (IL4), nuclear factor kappa B1 (NFKB1) and protease-activated receptor 1 (PAR1)." (PMID 26879815, 2016). "TNF-α and IL-1α have been together implicated in a NF-κB-mediated signal cascade that inhibited apoptosis and increased the proliferation of epithelial cells in human prostate preneoplasia and cancer." (PMID 23991210, 2013). "Furthermore, IL-1α upregulation could reflect a proinflammatory microenvironment enriched in cancer-associated fibroblasts (CAFs) and immune infiltrates." (PMID 40940885, 2025). "Furthermore, elevated IL‐1A expression is linked to a bad prognosis for cancer." (PMID 38152044, 2024). "Thus, IL-1α has been considered a potential pathogenic factor involved in the development and progression of several disease including diabetes, inflammatory bowel disease, myocardial inflammation, and cancer." (PMID 31612270, 2020).